OR2AK2 (olfactory receptor family 2 subfamily AK member 2)
Description:
Odorant receptor.
Synonyms: OR2AK1P; OR1-47
Gene: Protein-coding gene on chromosome 1 (247,965,233 to 247,966,386, forward strand). Ensembl gene ENSG00000187080.
Subcellular location: Cell membrane
Pathways (Reactome):
Sensory Perception: Expression and translocation of olfactory receptors
Genetic constraint (gnomAD): Loss-of-function variants: 0 observed, 0.2 expected, observed/expected ratio (o/e) 0, 90% interval 0 to 1.88. That is too few expected variants to judge how well the gene tolerates losing a copy. Missense variants: 392 observed, 394.05 expected, observed/expected ratio (o/e) 0.99, 90% interval 0.92 to 1.08. Synonymous variants: 139 observed, 153.31 expected, observed/expected ratio (o/e) 0.91, 90% interval 0.79 to 1.04.
Homologues: Orthologues: chimpanzee OR2AK2 (99% identical), rat Or2ak5 (74% identical), rat Or2ak5d (73% identical), dog OR2AK3 (73% identical), mouse Or2ak5 (73% identical), rat Or2ak4 (73% identical), rat Or2ak5b (73% identical), mouse Or2ak4 (72% identical), mouse Or2ak7 (72% identical), rat Or2ak4c (72% identical), rat Or2ak4c (71% identical), rat Or2ak5f (71% identical), and 4 more. Paralogues in human: OR2L3 (56% identical), OR2L8 (55% identical), OR2L5 (54% identical), OR2L2 (53% identical), OR2T27 (53% identical), OR2L13 (52% identical), OR2T1 (50% identical), OR2M2 (50% identical), OR2M5 (50% identical), OR2M3 (49% identical), OR2M7 (49% identical), OR2V2 (48% identical), and 80 more.